LYSMD2 (LysM domain containing 2)
Synonyms: MGC35274
Tractability: PROTAC: its protein half-life has been measured.
Gene: Protein-coding gene on chromosome 15 (51,723,011 to 51,751,585, reverse strand). Ensembl gene ENSG00000140280.
Subcellular location (Human Protein Atlas): Mitochondria; Nuclear bodies
Genetic constraint (gnomAD): Loss-of-function variants: 4 observed, 10.19 expected, observed/expected ratio (o/e) 0.39, 90% interval 0.19 to 0.9. The upper end of that interval is the gene's LOEUF score, 0.9, which puts it in group 3 of 6, group 1 being the genes least tolerant of losing a copy. Missense variants: 219 observed, 197.94 expected, observed/expected ratio (o/e) 1.11, 90% interval 0.99 to 1.24. Synonymous variants: 97 observed, 84.1 expected, observed/expected ratio (o/e) 1.15, 90% interval 0.98 to 1.37.
Homologues: Orthologues: chimpanzee LYSMD2 (100% identical), pig LYSMD2 (91% identical), rabbit LYSMD2 (91% identical), dog LYSMD2 (90% identical), mouse Lysmd2 (89% identical), rat Lysmd2 (87% identical), macaque LYSMD2 (67% identical), guinea pig LYSMD2 (65% identical), tropical clawed frog lysmd2 (60% identical), zebrafish lysmd2 (59% identical), Caenorhabditis elegans lmd-1 (15% identical), Drosophila melanogaster CG17985 (15% identical). Paralogues in human: LYSMD1 (37% identical), LYSMD3 (21% identical), LYSMD4 (16% identical).
Diseases named in the same sentence as LYSMD2 in open-access papers:
LYSMD2 is named in the same sentence as 1 disease in open-access papers, as found by Europe PMC text mining. Sharing a sentence is not in itself a finding about the gene and the disease. The quoted sentences say what the papers report.
melanoma (1 paper, 2022). A malignant, usually aggressive tumor composed of atypical, neoplastic melanocytes. "Only five genes were found to be predictive of good outcome when highly expressed in melanoma: LYSMD2, PSPIP2, SNAP23, TSHR, and CCPG1." (PMID 36553569, 2022).